CCL20 (C-C motif chemokine ligand 20)
Diseases named in the same sentence as CCL20 in open-access papers (continued):
Sharing a sentence is not in itself a finding about the gene and the disease.
acute kidney injury (4 papers, 2021 to 2025). Sudden and sustained deterioration of the kidney function characterized by decreased glomerular filtration rate, increased serum creatinine or oliguria. "Urinary CCL20 was also increased in patients with acute kidney injury and was associated with renal severity." (PMID 38990435, 2025). "CCL20 is expressed in tubular, endothelial, and interstitial cells, and has been reported to be upregulated in human kidneys with acute kidney injury." (PMID 38990435, 2025). "CCL20 is expressed by tubular endothelial and interstitial cells and is also upregulated in kidneys with acute kidney injury." (PMID 34356678, 2021). "CC motif chemokine ligand 20 (CCL20), a chemokine involved in immune cell migration through its receptor CCR6, has been implicated in kidney inflammation in crescentic glomerulonephritis and acute kidney injury." (PMID 41226600, 2025).
breast invasive carcinoma (4 papers, 2019 to 2024). "We used immunohistochemistry to quantitate FOXP3, CD4, and CCL20 expression in 156 invasive breast cancers samples." (PMID 31852159, 2019).
Cognitive impairment (4 papers, 2021 to 2025). Abnormal cognition is characterized by deficits in thinking, reasoning, or remembering. "However, the role of CCL20 in cognitive disorders is unclear." (PMID 39011039, 2024). "In this paper, we review the roles and regulatory mechanisms of pro-inflammatory chemokines (CCL2, CCL3, CCL4, CCL5, CCL11, CCL20, and CXCL8) in cognitive impairment." (PMID 39011039, 2024).
dyslipidemia (4 papers, 2021 to 2023). "HFD feeding tended to elevate Ccl20 expression in the skin, whereas Apoe deficiency-mediated dyslipidemia upregulated Il19 expression in the skin." (PMID 37646025, 2023). "HFD feeding elevated Ccl20 expression, whereas Apoe-deficiency-mediated dyslipidemia upregulated Il19 expression in the skin without IMQ application." (PMID 35457132, 2022). "Rifaximin treatment reduced serum levels of several proinflammatory interleukins (IL) such as IL22 and CCL20 in both groups of patients, while IL17 and CXCL13 were only reduced in patients without metabolic syndrome manifestations." (PMID 35165326, 2022).
endometrial cancer (4 papers, 2016 to 2023). Primary or metastatic malignant neoplasm involving the endometrium (mucous membrane that lines the endometrial cavity). "In endometrial cancer, CCL20 mediates RANK/RANKL-induced epithelial-mesenchymal transition (EMT) and tumor metastasis." (PMID 33123272, 2020). "N-cadherin was over expressed when endometrial cancer cells were treated with TGF-β, IL-6, chemokines CCL18, RANK/RANKL/CCL20, and CXCR4/CXCL12." (PMID 36766756, 2023). "The studies included have demonstrated a downregulation of epithelial marker E-cadherin in endometrial cancer cells by TGF-β treatment, AMF treatment, and IL-6 treatment and when treated with chemokine CCL18 and RANK/RANKL/CCL20." (PMID 36766756, 2023). "RANK overexpressed endometrial cancer cells had higher levels of CCL20 which facilitates invasion and EMT of RANK overexpressed endometrial cancer cells." (PMID 34951691, 2022).
endothelial dysfunction (4 papers, 2020 to 2024). In vascular diseases, endothelial dysfunction is a systemic pathological state of the endothelium (the inner lining of blood vessels) and can be broadly defined as an imbalance between vasodilating and vasoconstricting substances produced by (or acting on) the endothelium. "Other pathogenic effects of IL-17A on endothelial dysfunction include the induction of the gene expression of chemokines and pro-inflammatory mediators, including IL-8, CCL20, IL-6 and IL-15." (PMID 33322218, 2020). "During atherogenesis, endothelial dysfunction elevates local CCL20 levels, directing CCR6 cells (B cells, immature dendritic cells, innate lymphoid cells (ILCs), regulatory CD4 T cells, and Th17 cells) to the subendothelial space." (PMID 39335632, 2024).
eosinophilia (4 papers, 2009 to 2021). "First, an experimental model of OVA-induced AHR, airway eosinophilia, and type 2 cytokine production was used to monitor the activities of CCL20 and CCR6+ Treg cells." (PMID 34497608, 2021). "In AD patients below 10 years old (Group 1) a positive correlation between eosinophilia and CCL-20 (r = 0.53, P = .009) and IL-18 (r = 0.45, P = .03) was noted while in Group 2 eosinophilia correlated positively with CCL-27 (r = 0.52, P = .03)." (PMID 19639049, 2009). "It is also reported that the CCL20/CCR6 system plays a pivotal role in allergic airway responses such as airway resistance, airway eosinophilia, and production of IL-5 and IgE." (PMID 22013453, 2011). "It has also been reported that the CCL20/CCR6 system may play a pivotal role in allergic airway responses such as AHR, airway eosinophilia, and production of IL-5 and IgE." (PMID 28628664, 2017).
gingivitis (4 papers, 2018 to 2023). A disorder involving inflammation of the gums; may affect surrounding and supporting structures of the teeth. "Secretion of CCL20 by the gingiva equivalents was increasedafter the exposure to the commensal and gingivitis biofilms." (PMID 28892653, 2018). "CCL20 is also among the chemokines being increased in experimentally induced gingivitis that might become a target of EMD therapy." (PMID 37762294, 2023).
glomerulonephritis (4 papers, 2016 to 2024). A renal disorder characterized by damage in the glomeruli. "We utilized photoconversion of intestinal cells in Kaede mice to track intestinal T cell mobilization upon glomerulonephritis induction, and we found that Th17 cells egress from the gut in a S1P-receptor-1-dependent fashion and subsequently migrate to the kidney via the CCL20/CCR6 axis." (PMID 27851911, 2016). "This is in line with a recent study demonstrating that the CCL20/CCR6 axis also mediates renal recruitment of Tregs, and that the reduction of anti-inflammatory Tregs in the presence of a fully functional Th1 response aggravates experimental glomerulonephritis." (PMID 27851911, 2016).
Hyperglycemia (4 papers, 2014 to 2025). An increased concentration of glucose in the blood. "In the current study, we demonstrate that blockade of KCa3.1 inhibited hyperglycemia induced up-regulation of CCL20 in both in vitro and in vivo models." (PMID 24733189, 2014). "In stratified analyses, in non-diabetic AMI patients stress hyperglycemia at admission was independently associated with the cytokines IL-6, IL-8, IL-10, CCL20, and MCP-1." (PMID 39962379, 2025). "Furthermore, this study showed higher levels of CCL20 with increasing stress hyperglycemia." (PMID 39962379, 2025). "Hyperglycemia-induced cytokines included T1/Th17 cytokines (IFN-γ, IL-17A, and CCL-20) that echo a T2D profile (black bars, right)." (PMID 38794641, 2024). "In Müller cells exposed to hyperglycaemia, the protein levels of MCP-1, soluble ICAM-1, CCL20, growth-regulated oncogene/cytokine-induced neutrophil chemoattractant-1 (GRO/CINC-1), VEGF and IL-6 were increased compared to normoglycaemic controls." (PMID 26222724, 2015).
IgA nephropathy (4 papers, 2014 to 2019). "HMCs stimulated by IgA1 can produce CCL20 and consequently recruit inflammatory Th17 cells to the kidneys to induce further lesions in IgA nephropathy." (PMID 31317046, 2019). "CCL20, as a chemokine, regulates inflammatory responses by recruiting Th17 cells, which has been previously shown in animal models of IgA nephropathy, dry eye disease, and acute viral myocarditis." (PMID 27334337, 2016). "Therefore, HMC stimulated by IgA1 could produce CCL20 and consequently recruit inflammatory Th17 cells to the kidneys to induce further lesion in IgA nephropathy." (PMID 28552941, 2017).
injury (4 papers, 2019 to 2022). Damage inflicted on the body as the direct or indirect result of an external force, with or without disruption of structural continuity. "Previous studies have found that CCL20 is closely related to neurodegenerative diseases after traumatic brain injury." (PMID 34792838, 2022). "IL-8 is involved in neutrophil recruitment, as in acute-liver injury whereas chemokine (C-C motif) ligand 20 (CCL20) and monocyte chemoattractant protein (MCP-1) attract dendritic cells, T cells and monocytes, as in chronic liver injury." (PMID 31182764, 2019).
Insulin resistance (4 papers, 2015 to 2024). Increased resistance towards insulin, that is, diminished effectiveness of insulin in reducing blood glucose levels. "Moreover, intermuscular fat, a marker which is associated with insulin resistance and metabolic dysfunction, was correlated with CCL20, IL-1RA and VEGF-A." (PMID 33540635, 2021).
lung disease (4 papers, 2013 to 2021). "Recently elevated levels of CC chemokines MCP-1(CCL2), MIP-1α,(CCL3), MIP-1β and (CCL4) and MIP-3α (CCL20) were reported in BALF of young children with CF with little apparent lung disease or infection." (PMID 24216293, 2013). "In contrast to DFO, extracellular GSH did reduce a subset of pro-inflammatory factors by more than 10-fold, including the pro-inflammatory cytokines CCL20, CSF-1, and MCP-1 that in BALF from CF infants are correlated with oxidative stress and lung disease." (PMID 33613309, 2021).
myocardial infarction (4 papers, 2019 to 2024). Gross necrosis of the myocardium, as a result of interruption of the blood supply to the area, as in coronary thrombosis. "Additional studies showed that GPR65 alleviated myocardial infarction-induced inflammation through inhibiting resident macrophage secretion of CCL20, a chemokine for γδT cells." (PMID 39336742, 2024). "This study was aimed to investigate the effects of CXCL9/CCL20 on cardiac fibrosis following myocardial infarction (MI)." (PMID 31083544, 2019). "microRNA (miR)-19a targets CC chemokine ligand 20 (CCL20) in myocardial infarction." (PMID 38961881, 2024). "The expression of GPR65 in cardiovascular diseases confers a protective action against myocardial infarction through transcriptional downregulation of the chemokine CCL20’s expression in macrophages, which, in turn, downregulates the production of pro-inflammatory IL17A." (PMID 39336742, 2024).
oral cancer (4 papers, 2015 to 2021). "We previously investigated the ways CCL20 increases modulated cell migration and invasion in oral cancer cells." (PMID 33802643, 2021). "Querying the TCGA HNSCC dataset we identified 8 potential mRNA targets (ESM1, KLF4, IL8, CCL20, IL24, CCNA1, TIMP4 and MMP1) from our validated 20 mRNA panel, which were aberrantly expressed in HNSCC and controlled by CELF1 in oral cancer cells." (PMID 26498364, 2015).
schizophrenia (4 papers, 2020 to 2025). A major psychotic disorder characterized by abnormalities in the perception or expression of reality. "The decreased IL-1β-induced CCL20 secretion by schizophrenia iPSC-astrocytes cause potential attenuating effects on recruitment of Tregs." (PMID 32802190, 2020). "A study of patients with schizophrenia reported that IL-1B exposure led to decreased chemotactic effect on T cells, suggesting astrocyte-derived chemokine CCL20 may be the cause of neuroinflammation in psychotic illness." (PMID 36358439, 2022). "Our research showed that patients with schizophrenia had much higher levels of certain immune markers, such as IL-17, IL-8, IL-22and CCL20." (PMID 41200225, 2025). "Upregulation of CCL20 is a highly interesting candidate mechanism potentially specific for schizophrenia and further knowledge is needed on the implications of altered peripheral levels of CCL20 in patients with SZ." (PMID 34584171, 2021). "Our results, along with other evidence from the literature, support the idea that CCL20 is a key chemotactic driver in Th17-related neuroimmune activation in schizophrenia and could be a good target for immunomodulation." (PMID 41200225, 2025). "CCL20 may be a novel and specific biomarker of schizophrenia, but an influence of antipsychotic medication cannot be excluded." (PMID 34584171, 2021). "The present study compares the serum levels of selected cytokines and chemokines—IL-17, IL-22, IL-23, IL-8, IL-21, CCL20, CXCL10, CCL2and CCL5—in schizophrenia patients to healthy controls due to growing evidence linking immune-inflammatory and metabolic dysregulation to schizophrenia." (PMID 41200225, 2025). "This study aimed to examine serum levels of Th17-related cytokines (IL-17, IL-21, IL-22, IL-23) and chemokines (CCL2, CCL5, CCL20, CXCL10, IL-8) in schizophrenia patients compared to healthy controls and to explore their associations with symptom severity and laboratory parameters." (PMID 41200225, 2025).
steatosis (4 papers, 2021 to 2024). Increased lipid within the cytoplasm of cells. "The CCL20 gene is also implicated in steatosis adverse outcome pathways (AOP)." (PMID 38953992, 2024). "In summary, hepatic IL-32 and CCL20 expression is increased in MASH samples with progressed activity (intense steatosis and moderate-to-severe fibrosis), and enhanced IL-32 expression was found to be related to the PNPLA3 I148M variant." (PMID 37686029, 2023). "Furthermore, a positive correlation was observed between IL-32 expression and steatosis grade, and between IL-32 as well as CCL20 expression and fibrosis grade." (PMID 37686029, 2023). "Interestingly, a positive correlation between steatosis grade and the expression of CCL20 was observed in non-carriers of the I148M variant." (PMID 37686029, 2023). "Th17/22 cells then release cytokines, including IL-6, IL-17, IL-22, tumor necrosis factor-α (TNF-α), TGF-β and C-C motif chemokine ligand 20 (CCL20), in mouse models of NASH and in patients with steatosis, which further promote tissue inflammation and recruitment of leucocytes." (PMID 34944732, 2021). "Additionally, CCL20 expression did not correlate with steatosis grade, but with fibrosis stage and tissue inflammation status (inflammatory cells)." (PMID 37686029, 2023). "The plasma level of NT‐3, CCL20, CCL4, CCL3, LIF‐R, OPG, and HGF was higher, and SCF was lower only in the severe steatosis versus no steatosis." (PMID 35128832, 2022).
vitiligo (4 papers, 2022 to 2026). Generalized well circumscribed patches of leukoderma that are generally distributed over symmetric body locations and is due to autoimmune destruction of melanocytes. "Increased levels of CCL20 were also reported in serum and vitiligous skin from patients with vitiligo, and CCL20 levels were significantly higher in patients with active vitiligo." (PMID 35096274, 2022). "Additionally, CCL20 concentrations were increased in the blister fluid of vitiligo patients compared to controls." (PMID 36911664, 2023). "Furthermore, IL-17 reveals CCL20, a chemokine that can introduce cytotoxic CD8+ T cells into peripheral tissues from the systemic circulation; these cells are responsible for melanocyte destruction in vitiligo." (PMID 39201060, 2024). "However, the authors hypothesized that CCL20 may be involved in the recruitment of dual producing IL-17 and IFN-γ cells (CCR6+ Th1/17 cells and Tc1/17 cells) to vitiligo skin." (PMID 36911664, 2023). "CCL20/CCR6 signaling recruits also Tregs to the skin and Tregs lacking CCR6 have a decreased capacity to migrate to vitiligo skin and suppress depigmentation." (PMID 36911664, 2023).
abdominal aortic aneurysm (3 papers, 2017 to 2026). Enlargement and ballooning of the vessel that supplies arterial blood to the abdomen, pelvis and legs. "MiR-143-5p has been reported to have a suppressive effect on macrophage M1 polarization and inflammation in abdominal aortic aneurysm, as miR-143-5p overexpression could suppress the expression of CCL20 and then promote the M2 polarization and inhibit the inflammation of macrophage." (PMID 41372998, 2025).
adenoma (3 papers, 2011 to 2025). A neoplasm arising from the epithelium. "CXCL1, CXCL2, CXCL3, CCL20, and IL-8 had increased expression in the adenoma and adenocarcinoma compared to normal colonic mucosa." (PMID 21249124, 2011). "CCL20 followed a similar pattern, but statistical significance was only observed in the paired analysis (59% of adenomas had higher expression, p = 0.031) and not in the bulk comparison." (PMID 40699620, 2025).
Airway obstruction (3 papers, 2009 to 2023). Obstruction of conducting airways of the lung. "CCL20 is involved in the pathogenesis of ILD and COPD, and Granulocyte-CSF links destructive inflammation and comorbidities in obstructive lung disease." (PMID 37460469, 2023).
allergic asthma (3 papers, 2021 to 2022). A asthma with a basis in a pathological type I hypersensitivity reaction. "Human allergic asthma constitutes an inflammatory microenvironment enriched with chemokines, such as CCL20, which promotes the migration of circulating CCR6+ Treg cells." (PMID 34497608, 2021). "Consistently with our analyses of the induced sputum, only patients with allergic asthma showed higher levels of CCL20 expression." (PMID 34497608, 2021). "This relative defect of circulating Treg subsets in patients with allergic asthma could result from the recruitment by CCL20 derived from inflammatory lungs." (PMID 34497608, 2021). "The production of CCL20 in human nasal epithelial cells may increase after stimulation dsRNA, and the upregulation of CCL20 expression may contribute to the recruitment and retention of effector T cells in allergic asthma." (PMID 35246242, 2022). "In the current study, we did not observe any difference of CCL20 expression between OVA-induced allergic asthma and control mice." (PMID 34497608, 2021).
Alzheimer disease (3 papers, 2017 to 2026). A progressive, neurodegenerative disease characterized by loss of function and death of nerve cells in several areas of the brain leading to loss of cognitive function such as memory and language. "This cell-based litmus gene assay identified six genes (CCL20, CEMIP, IL1B, IL8, PRG2, PTGS2) as potential biomarkers of plasma quality control and the SPC25 gene as a diagnostic biomarker of Alzheimer’s disease (AD)." (PMID 29203810, 2017).
astrocytoma (3 papers, 2022 to 2024). "In accordance with our findings in macrophages, P2Y11/IL-1R- or P2Y11/CXCR7-driven CCL20 production in astrocytoma cells depended on EGFR as well as on ERK and appeared to occur in an EGFR/CXCR7-ligand-independent manner." (PMID 38472446, 2024). "Consistent with the absence of CXCR4 and the resulting lack of requirement for PDE4 inhibition, a ten-fold lower concentration of IL-1ß was sufficient to induce high levels of CCL20 in the astrocytoma cells." (PMID 38472446, 2024). "In astrocytoma cells, the CCL20-enhancing effect of TC14012 can only be mediated by CXCR7, as these cells lack CXCR4." (PMID 38472446, 2024). "In fact, CCL20 was among the most highly activated genes in response to ectopic P2Y11 stimulation in astrocytoma cells." (PMID 36107259, 2022). "In the astrocytoma cell line CXCR7 knockdown diminished CCL20 production." (PMID 38472446, 2024). "To clarify the mechanism of TC14012-enhanced CCL20 production, we took advantage of a P2Y11-recombinant astrocytoma cell line, which we already used in our previous studies." (PMID 38472446, 2024). "In line with our hypothesis that CXCR4 has regulatory effects, P2Y11/IL-1R signaling was sufficient to induce CCL20 production in astrocytoma cells with no requirement for PDE4 inhibition." (PMID 38472446, 2024). "Using an astrocytoma cell line, naturally expressing CXCR7 but lacking CXCR4, P2Y11/IL-1R activation effectively induced and CXCR7 agonist TC14012 enhanced CCL20 production even in the absence of PDE4 inhibition." (PMID 38472446, 2024).
brain injury (3 papers, 2019 to 2024). Acute and chronic (see also brain INJURIES, CHRONIC) injuries to the brain, including the cerebral hemispheres, CEREBELLUM, and brain STEM. "However, it is still necessary to test whether and how blocking CCR6 and CCR8 affects the activities of their endogenous ligands, which are known to be upregulated, as is well documented for CCL1 and CCL20 after nerve and brain injury, respectively." (PMID 38612597, 2024).